ATR (ATR checkpoint kinase)
Diseases named in the same sentence as ATR in open-access papers (continued):
Sharing a sentence is not in itself a finding about the gene and the disease.
cancer (continued). "Ionizing radiation-induced DNA double-strand breaks (DSBs) increased the expression of SERPINE1 in cancer cells in an ATM/ATR-dependent manner, and promoted nuclear localization of SERPINE1 to facilitate DSB repair." (PMID 36681663, 2023). "Adavoserib synergizes with ATR inhibitor ceralasertib (AZD6738) in killing cells of various cancer origins." (PMID 36975505, 2023). "Members of the cytosolic Fe/S assembly pathway- MMS19 and CIAO2B were found to be essential for replication stress tolerance of cancer cells towards Chk1 and ATR inhibition." (PMID 37810966, 2023). "Key exclusion criteria included treatment with chemotherapy; small molecule or biologic anti-cancer therapy within 14 d before first dose of the study drug; or prior therapy with an ATR or DNA-dependent protein kinase (DNA-PK) inhibitor." (PMID 37277454, 2023). "Multiple ATR inhibitor (ATRi)-sensitizing cancer alterations have been proposed by means of RNA interference-enabled or CRISPR–Cas9-enabled forward chemogenomic screening." (PMID 37277454, 2023). "Our previous study first showed that ATR-binding long noncoding RNA (lncRNA) is necessary for ATR function and promotes cancer resistance." (PMID 37775817, 2023). "This leads to induction of excessive genome instability, micronuclei formation and cell death, a sequence observed with different ATR inhibitors and across cancer types." (PMID 36975505, 2023). "In other words, during prolonged inhibition of ATR or Chk1 (such as during clinical treatment) Myt1 levels can determine the drug sensitivity of cancer cells and, as a consequence, the efficacy in cancer therapy." (PMID 38020882, 2023). "Here, we investigate the intrinsic expression of STING in cancer cells and evaluate the value of the combination of ATR and TOP1 inhibitors in enhancing antitumor immunity." (PMID 35957613, 2023). "The multiple studies of HORMAD1 function in tumors suggest a mixture of genomic protection and disruption, depending on the stage and type of cancer or additional changes in DNA repair pathways (BRCA1/2 mutation, ATM/ATR loss, and so on)." (PMID 37838177, 2023). "In this study, we have assessed presentation of three hallmark factors for immunogenic cell death – namely release of HMGB1, secretion of ATP and surface-presentation of CALR – in human cancer cell lines after treatment with radiation and ATR inhibitors." (PMID 37346039, 2023). "Deregulation of the ATR checkpoint and aberrant levels of chronic replication stress is a common characteristic of cancer and a point of vulnerability being exploited in cancer therapy." (PMID 37445667, 2023). "Key molecules, including PARP, ATM/ATR, amplified/overexpressed transcription factors, and DNA methyltransferases, maintain the cancer genome and keep abnormal DNA replication and cell division operating, while escaping critical DNA damage and cell death." (PMID 37514113, 2023). "The direct testing of ATM-deficient PCa models have demonstrated sensitivity to ATR inhibitors that was further potentiated by the addition of PARP inhibitor, a combinatorial effect that has been observed in several cancer types." (PMID 38201511, 2023). "In 2016, an Australian team published the results of the sequencing of a cancer gene panel comprising ATR for 2000 BC cases with a strong familial history, WT for BRCA1/2 and 1997 healthy controls." (PMID 36749285, 2023). "In conclusion, ATR kinase has emerged as a promising target for cancer therapy, and the area of ATR inhibition (ATRi) is quickly expanding, with multiple early-phase clinical studies now underway." (PMID 37511442, 2023). "We conclude that FBXW7-mutant cells from multiple cancer types are more sensitive to ATR inhibition, which is broadly applicable to several cancer types, revealing a druggable synthetic lethal interaction between DNA repair genes and FBXW7 mutations." (PMID 38032106, 2023).
cancer (continued). "We have elucidated the synthetic lethal interactions between FBXW7 mutation and DNA damage response genes, and highlighted the potential of ATR inhibitors as targeted therapies for cancers harboring FBXW7 alterations." (PMID 38032106, 2023). "Basic functions of ATR classify it in the category of tumor suppressor genes but further studies show that its role is more complex in the context of cancer." (PMID 36749285, 2023). "Because of the substantial replication stress of cancer cells, ATR is considered an attractive target for anticancer therapy and selective ATR inhibitors that are currently in clinical trials include berzosertib (M6620, VX-970) and elumusertib (BAY-1895344)." (PMID 37637936, 2023). "We observed that the protein levels of FANCD2, RAD51, and ATR, which promote alternative end-joining, DNA damage repair, and cancer cell survival, were downregulated." (PMID 37020276, 2023). "Most cancer cells have unregulated G1 checkpoints, making them dependent on the S and G2 checkpoints, which are activated through ATR/CHK1 signaling pathways." (PMID 36765714, 2023). "ATR is frequently expressed at high levels in cancer stem cells playing a crucial role in maintaining their stemness." (PMID 37349788, 2023). "ATR plays a central role in the response to RS, DNA damage response (DDR) and cell cycle control making it a logical and likely candidate for cancer predisposition." (PMID 36749285, 2023). "PIKK members ATM, ATR, and DNA-PK are closely related to DNA damage repair and have complex effects on cancer progression and treatment." (PMID 37489050, 2023). "Specific small molecule inhibitors for each kinase were developed and several inhibitors of ATR and DNA-PKcs are currently being tested in many cancer types as monotherapies or in combination therapies with genotoxic agents." (PMID 38201511, 2023). "In order to exploit the effect of ATR suppression on cancer treatment, an ATR-Seckel mouse model has been used." (PMID 37511442, 2023). "The inhibition of poly(ADP-ribose) polymerases (PARPs) and ataxia telangiectasia and Rad3-related (ATR) would be an alternative approach for cancer treatments." (PMID 36794257, 2023). "The ATR inhibitor berzosertib shows potent preclinical anticancer effects in several cancers and is well tolerated in clinical studies." (PMID 37934325, 2023). "Lung cancer cells that acquire Adavosertib resistance have also been reported to have upregulated ATR and Chk1 activity, which suggests that these kinases also play an important role in determining cancer cell sensitivity to Adavosertib." (PMID 38020882, 2023). "A deficiency in ATM or its low expression is a biomarker of sensitivity to PARP or ATR inhibitors in cancer and the ATM-selective inhibitor AZD-1390 is currently in clinical trials." (PMID 37637936, 2023). "As another important avenue of DNA damage response involved in cell cycle control, mutations in ATR and CHEK1 also have roles in the development of certain cancers." (PMID 36358700, 2022). "In vitro, ATR inhibition downregulates radiotherapy-induced programmed death-ligand 1/2 (PD-L1/2) expression to sensitise cancer cells to T-cell killing, in addition to potentiating DNA damage." (PMID 36106115, 2022). "Because of the critical functions of ATR in protecting cells under replication stress, small-molecule ATR inhibitors are being explored as cancer therapeutic agents to selectively kill cancer cells under replication stress." (PMID 36381660, 2022).
cancer (continued). "As several ATR inhibitors have entered into clinical studies, targeting ATR holds promise to treat ARID1A mutated cancers." (PMID 36123603, 2022). "The present data show that combining ionizing radiation with ATR inhibitors is highly effective in eradicating ARID1A- CRC cancer cells." (PMID 36249060, 2022). "Hypersensitivity of ATM-defective cells to IR and the critical function of the ATR pathway for the survival of tumor cells has led to considerable interest in ATM and ATR as therapeutic targets for cancer therapy." (PMID 35406593, 2022). "Inhibitors of ATR or Chk1 are currently being evaluated as anticancer treatments in cancers harboring high levels of RS, such as hematological cancers." (PMID 35228749, 2022). "There are over twenty CHK1/2 and ten ATR inhibitors in various stages of clinical trials for many different cancer types mostly in combination with chemotherapy but also with RT and histone deacetylase inhibitors (HDACi)." (PMID 36276148, 2022). "To further demonstrate the utility of ZetaSuite in analyzing the DRIVE and DepMap datasets to mine important cancer pathways, we analyzed two separate clusters connected by ATR, a key regulator of genotoxic stress." (PMID 35879727, 2022). "Secondly, we identified associations with sensitivity to ATR inhibitors AZD6738, VE-822, VE-821 or k.o. of the ATR gene in four cancer types." (PMID 35614096, 2022). "Increased immune effects, such as activation of CD8+ T cells and immunological memory, have been observed in murine cancer models after treatment with the ATR inhibitor AZD6738 and ionizing radiation (IR)." (PMID 36387237, 2022). "Double strand break (DSB) repair is sufficient to induce PD-L1 expression in cancer cells through ATR/Chk1 signaling axis." (PMID 35646698, 2022). "In recent years, the inhibition of ATR has been proven to be effective in cancer therapy in preclinical and clinical studies." (PMID 35458687, 2022). "Similar compounds of these novel classes of drugs targeting ATR and DNA-PK have already demonstrated a radiosensitizing effect in various types of cancer cells." (PMID 35740300, 2022). "We also discuss how targeting helicase in combination with DNA repair inhibitors (i.e., PARP and ATR inhibitors) can be used as novel approaches for cancer treatment to increase sensitivity to current treatment to prevent rise of treatment resistance." (PMID 35267530, 2022). "In recent years, ATR inhibitors have been used in many cancer investigations, and their roles in cancer treatment have gradually been realized." (PMID 36082941, 2022). "According to “The Human Protein Atlas”, ATR protein has low cancer specificity, which means that its expression is dysregulated in almost all cancer types." (PMID 35458687, 2022). "The dependency of cancer cells on the intra S-phase checkpoint has led to the development of ATR and CHK1 inhibitors." (PMID 35393546, 2022). "Depletion of TopBP1 in some specific cancer cells enhanced ATR/CHK1 activation and S-phase checkpoint response after RS." (PMID 35875060, 2022). "In contrast with the early stages of tumorigenesis, later stage cancer cells need to acquire mechanisms that allow them to cope with high levels of genomic instability, and consequently can become addicted to the ATR/CHK1 pathway." (PMID 36240068, 2022). "To date, the majority of the studies testing DDR inhibition for clinical purposes are in cancer field, and several ATR inhibitors have been proposed." (PMID 35811699, 2022). "Cancer cells driven by oncogenes are hyperdependent upon the ATR/CHK1/WEE1 signaling pathway, which enables them to attenuate RS." (PMID 36253861, 2022).
cancer (continued). "Recently, ATM and ATR inhibitors are highlighted as antitumor agents because numerous cancers, including CRC, utilize the ATM/ATR‐associated DDR for survival and drug resistance." (PMID 35384384, 2022). "DSBs induced by ionizing radiation or treatment with DNA damaging agents has recently been shown to lead to an increase of PD-L1 expression in cancer cells via an ATM/ATR/Chk1-dependent mechanism." (PMID 35646698, 2022). "The inhibition of cell cycle checkpoint proteins, such as ataxia telangiectasia mutated and Rad3-related kinase (ATR) and its major downstream effector checkpoint kinase 1 (CHK1), is another strategy to increase the anti-cancer efficacy of TOP1-ADC." (PMID 36015333, 2022). "Similar synergies between ATR inhibitors and chemotherapeutic agents have been identified in other cancer cell types." (PMID 36413415, 2022). "Disruption of ATR function impacts cancer cell survival in both the absence and the presence of DNA-damaging agents." (PMID 35178190, 2022). "To test the feasibility of ATR inhibition in the treatment of high-grade neoplasms, we evaluated NF1- and ATRX-deficient cancer cells." (PMID 35740680, 2022). "Multiple studies have shown that PD-L1 upregulation in cancer cells is ATM/ATR/Chk1-dependent and induced by IR or treatment with some DNA-damaging agents." (PMID 36497387, 2022). "Inhibition of PIKK family member ATR is a promising cancer treatment strategy for tumors that manifest ATR-dependent DNA damage response defects and replication stress." (PMID 36273589, 2022). "Other highly mutated HR-related genes, including RAD51B (mutation frequency in patients, 6.1%), ATR (6.1%), ATM (6.1%), PALB2 (6.1%), and BRIP1 (4.9%), have been reported to be capable of affecting the sensitivity of various cancer cells to PARPis." (PMID 35952757, 2022). "In particular, alongside the traditional concept of targeting DDR enzymes such as PARP1, WEE1, and ATR, harnessing the epigenomic changes in cancer cells represents another exciting direction as DNA damage repair largely depends on chromatin configuration." (PMID 36123603, 2022). "Proteins implicated in HR repair pathway were frequently mutated in human cancers, such as BRCA1/2, ATM/ATR, RAD51, FA proteins, and others." (PMID 35952757, 2022). "Berzosertib, an ATR inhibitor, is found to have an effect on cancer therapy and is settled in a multicenter, open‐label, randomized, phase II trial." (PMID 36349142, 2022). "Collectively, these results confirm the proposed mechanism of action for MTHFD2 inhibitors via induction of RS and provide rational support for the potential future use of MTHFD2 inhibitors as cancer-selective sensitizers to ATR-signaling blockade therapies." (PMID 35228749, 2022). "Thereby, ATR inhibitor has potential utility for the treatment of various cancers, either alone or in combination with other therapies." (PMID 35458687, 2022). "Pharmacological inhibition of CTP synthase induces selective replication stress in MYC‐overexpressing cancer cells and synergizes with ATR inhibitors to kill them." (PMID 36214609, 2022). "Torin2 is a potent inhibitor of mTOR, ATM, and ATR and has been previously shown to inhibit the growth of several different cancers." (PMID 35406510, 2022). "Across 16 cancer cell lines from different histologies, cells with high repstress score showed higher sensitivity to ATR inhibitor M4344 than cells with low repstress score (Spearman r = 0.88, P < 2.0 × 10−16)." (PMID 36381660, 2022). "Multiple cancer‐related ATR synthetic lethal effects have been described that, at least in part, provide the rationale for the clinical use of ATRi in biomarker‐defined subsets of patients." (PMID 35567571, 2022). "Common enrichment pathways are cell cycle checkpoints, resolution of sister chromatid cohesion, mitotic prometaphase, retinoblastoma gene in cancer, cell cycle, mitotic spindle checkpoint, M phase, DNA irdamage and cellular response via ATR." (PMID 35774795, 2022).
cancer (continued). "ATR further activates the ATR-Chk1 pathway, thereby preventing DNA from further damage, and is thus essential to the survival of many cancers." (PMID 35563313, 2022). "ATR is considered an important direction in cancer therapy because of its deleterious effects on cancer cells that contain defects in homologous recombination." (PMID 36035159, 2022). "KRAS mutations and the overexpression of CCNE1, CCND2, and MYC genes induce hypersensitivity to ATR inhibitors in cancer cell lines." (PMID 36499000, 2022). "Treatment of cancer cells with either ATM or ATR inhibitors leads to a reduction in the levels of APOBEC3 activation." (PMID 34578402, 2021). "Cancer-associated SPOP mutations impair DNA replication surveillance and cause replication origin over-firing and re-replication, thereby increasing replication stress and sensitizing cancer cells to ATR inhibition." (PMID 34599168, 2021). "Inhibition of either ATM or ATR enhanced the effect of the combination of FUdR and DUTi on cancer cell lethality by 31.2% ± 6.1 (P = 0.0003) and 31.8% ± 6.1 (P = 0.0004), respectively." (PMID 33824328, 2021). "RS represents the initial insult from stalled or collapsed DNA replication forks during oncogenesis, which places ATR in a pivotal position to confront growing genomic instability within a developing cancer." (PMID 33811746, 2021). "Similar to our analysis, other studies have shown that the activation of ATR leads to cell survival and proliferation; thus, several inhibitors of ATR/CHK1 have been proposed to treat cancer." (PMID 34715892, 2021). "This drug induced tumor senescence in breast, lung, and colon carcinoma cell lines and verified the ATM/ATR signaling pathway to be constitutively active in cancer cells." (PMID 33912571, 2021). "Replication forks that are stabilized by ATR can be restarted after the removal of the stress, making ATR an attractive target for cancer therapy." (PMID 34676045, 2021). "Because mitomycin C (used in HIPEC) mainly induces interstrand crosslinks which activates ATR, the addition of ATR inhibitors to mitomycin C improved treatment efficacy on cancer organoids, identifying a potential new clinical strategy." (PMID 33816288, 2021). "VE‐821 is a ATR inhibitor with potent inhibitory activities on the phosphorylation of H2AX and CHK1 by ATR, and sensitizing effect on cancer cells to radiotherapy and genotoxic chemotherapeutics." (PMID 34977872, 2021). "The ATR DDR pathway is critical for duplicating DNA under stressful conditions, and ATR inhibitors as either monotherapy or combination therapy have been in different phases of clinical trials of cancer patients." (PMID 34796173, 2021). "Inhibiting the function of molecules operative in the DDR, such as ataxia telangiectasia and Rad3-related (ATR), ataxia telangiectasia mutated (ATM), and DNA-dependent protein kinase (DNA-PK), have successfully sensitized cancer cells to ionizing radiation." (PMID 34746010, 2021). "After more than a decade of delay between establishing that DDR proteins were desirable cancer therapy targets, potent and selective compounds eventually became available to target ATR, ATM and DNA-PK." (PMID 34298632, 2021). "Whereas ATR inhibitors with combinations of radiotherapy or chemotherapy have synergistic effects in cancer therapies, regulators/modulators of the ATR-Chk1 DDR pathway have also been targets for cancer therapy." (PMID 34796173, 2021). "Co-inhibition of POLH and the ATR serine/threonine kinase, another DDR protein, causes synthetic lethality in a range of cancers, reinforcing that POLH is an emerging target for the development of novel oncology therapeutics." (PMID 34900730, 2021).